TREML3P (triggering receptor expressed on myeloid cells like 3, pseudogene)
Synonyms: TLT3; formerly TREML3
Gene: Transcribed unprocessed pseudogene on chromosome 6 (41,209,634 to 41,217,947, reverse strand). Ensembl gene ENSG00000184106.
Diseases named in the same sentence as TREML3P in open-access papers:
TREML3P is named in the same sentence as 1 disease in open-access papers, as found by Europe PMC text mining. Sharing a sentence is not in itself a finding about the gene and the disease.
TREML3P shares sentences with these, for which no sentence is quoted: tumor (1 paper).